ENSG00000277599
Gene: Miscellaneous RNA gene on chromosome 11 (65,423,960 to 65,424,118, forward strand). Ensembl gene ENSG00000277599.
Gene Ontology:
Cellular component: paraspeckles